ATG4C (autophagy related 4C cysteine peptidase)
Diseases named in the same sentence as ATG4C in open-access papers (continued):
Sharing a sentence is not in itself a finding about the gene and the disease.
tumor (13 papers, 2017 to 2025). "The significantly weaker tumor suppressor role of Atg4C needs further research to establish the key function of the autophagy mechanism in tumor suppression." (PMID 32121322, 2020). "The univariate Cox regression model revealed that age, race, histologic grade, anatomic subdivision, venous invasion, residual tumor, clinical stage, expression of CAV1 and ATG4C mRNA were associated with prognosis of EOC patients in terms of OS (P<0.05)." (PMID 32401768, 2020). "The expression of Ki67, LC3 and ATG4C were decreased significantly in tumor tissues from sh-ATG4C group." (PMID 31291988, 2019). "The development of specific inhibitors of ATG4A and ATG4C may lead to new approaches for tumor treatment in the future." (PMID 34636718, 2021). "In previous studies, ATM and ATG4C were reported to have a tumor-suppressive role." (PMID 28423511, 2017). "Along similar lines, we surmise that ATG4C could also represent a valuable molecular target, as demonstrated by a large set of evidences suggesting that anti-autophagy compounds are effective in suppressing tumor growth and countering tumor resistance to chemotherapies." (PMID 28423511, 2017). "Mice that are hemizygous for BECN1 and those that lack Atg4C and BIF1 exhibit a heightened likelihood of tumor formation due to the absence of these autophagic factors." (PMID 40248706, 2025). "It was found first in mice hemizygous for BECN1 and later in mice lacking Atg4C and BIF1 that lack of these autophagic factors could lead to increased tumor formation incidence." (PMID 40248706, 2025).
cancer (7 papers, 2019 to 2025). A tumor composed of atypical neoplastic, often pleomorphic cells that invade other tissues. "The expression levels of CAV1 protein in stromal cells and ATG4C protein in cancer cells are significantly associated with histologic subtypes of EOC." (PMID 32401768, 2020). "Our study also showed a positive association between CAV1 and ATG4C protein expression in cancer cells and stromal cells separately." (PMID 32401768, 2020). "The ATG4 family (ATG4A, ATG4B, ATG4C, and ATG4D) encodes proteases essential for autophagy, a process implicated in cancer progression and drug resistance." (PMID 40883962, 2025). "The potential role of CAV1 and ATG4C in the formation and progress of cancers deserve further exploration." (PMID 32401768, 2020). "Altered expression of caveolin-1 (CAV1) and autophagy marker ATG4C is observed in various types of human cancers." (PMID 32401768, 2020). "Our results also revealed that CAV1 protein level in the stroma, ATG4C protein level in cancer cells, and high expression of both CAV1 and ATG4C proteins in the stroma were related to histologic subtypes of EOC." (PMID 32401768, 2020). "High expression of CAV1 protein in the stroma and ATG4C protein in cancer cells were found to be significantly related to the histologic subtypes of EOC patients (P = 0.019, P = 0.005, respectively)." (PMID 32401768, 2020). "Another isoform molecule of ATG4, ATG4C, has also been extensively studied in the field of cancer." (PMID 34636718, 2021). "Moreover, both CAV1 and ATG4C are active participators in the process of cancer cell migration and invasion." (PMID 32401768, 2020). "Moreover, CAV1 protein level in the stroma, ATG4C protein level in cancer cells, and high expression of both CAV1 and ATG4C protein in the stroma are correlated with histologic subtypes of EOC patients." (PMID 32401768, 2020). "Taken together, CAV1 and ATG4C may act as the targets or signaling molecules in cancer progression and contribute to cancer invasion and metastasis." (PMID 32401768, 2020). "There was a positive association between CAV1 and ATG4C protein expression in cancer cells (P<0.001, phi coefficient = 0.368); a positive correlation between CAV1 and ATG4C protein expression in stromal cells was also identified (P = 0.002, phi coefficient = 0.345)." (PMID 32401768, 2020). "Interestingly, ATG4C staining in cancer cells was strongly positive in the majority of serous EOC, which had poor prognosis, compared with the other histology subtypes." (PMID 32401768, 2020). "ATG4C and ATG4D have also been implicated in cancer biology." (PMID 31083460, 2019). "ATG4 (ATG4A, ATG4B, ATG4C and ATG4D), a cysteine protease family, plays a crucial role in autophagy signaling and correlated with cancer progression in different types of cancers." (PMID 37038218, 2023). "In conclusion, this is the first study that evaluates the clinical significance and prognostic value of CAV1/ATG4C for EOC patients, as well as their expression and distribution in both cancer cells and stromal cells." (PMID 32401768, 2020). "All 95 EOC samples were available for analysis of CAV1 and ATG4C immunostaining in cancer cells, of which 79(83.2%) cases had sufficient tissues for analysis of CAV1 and ATG4C immunostaining in stromal cells." (PMID 32401768, 2020).
infection (2 papers, 2017 to 2023). The state of being infected such as from the introduction of a foreign agent such as serum, vaccine, antigenic substance or organism. "At 6 h post-infection (hpi), the enriched pathways included proteasome, ribosome, and regulation of autophagy, with the core genes of the most significantly enriched pathway in autophagy regulation (FDR = 0.2325) including ATG12, PIK3C3, GABARAPL1, ATG4C, and ATG4A." (PMID 37515115, 2023).
bacterial infection (1 paper, 2016). "The array analysis revealed that many autophagy related mRNAs (i.e., LC3-II, Atg4C, and Atg16L2) were upregulated in macrophages, suggesting that autophagy may be involved in bacterial infection." (PMID 26735693, 2016).
ATG4C also shares sentences with these, for which no sentence is quoted: colorectal cancer (1 paper); colorectal tumors (1); dyslipidemia (1); gynecologic tumor (1); hepatocellular carcinoma (1); neuropathic pain (1); protein folding disorders (1); vitiligo (1).